TMEM256-PLSCR3 (TMEM256-PLSCR3 readthrough (NMD candidate))
Gene: Protein-coding gene on chromosome 17 (7,389,734 to 7,404,097, reverse strand). Ensembl gene ENSG00000262481.
Genetic constraint (gnomAD): Missense variants: 94 observed, 80.62 expected, observed/expected ratio (o/e) 1.17, 90% interval 0.99 to 1.38. Synonymous variants: 43 observed, 33.62 expected, observed/expected ratio (o/e) 1.28, 90% interval 1 to 1.65.